IL6 (interleukin 6)
Diseases named in the same sentence as IL6 in open-access papers (continued):
Sharing a sentence is not in itself a finding about the gene and the disease.
tumor (continued). "TDSFs, such as the vascular endothelial growth factor (VEGF), tumor necrosis factor alpha (TNF-α), transforming growth factor-β (TGF-β), and interleukins (ILs), such as IL-6 and IL-10, can derive from tumor cells, which are themselves induced by the local inflammatory microenvironment." (PMID 38391950, 2024). "Therefore, IL-6 blockade in combination with ICI can enhance the cytotoxic T lymphocyte response to the tumor and improve its control compared to ICI alone." (PMID 39544930, 2024). "We found elevations of IL-6 expression and Akt activation in TECs compared to NECs, suggesting that tumor-derived EVs may act on this pathway as a tumor microenvironment factor." (PMID 38318528, 2024). "M2-type macrophages then secrete epidermal growth factor receptor (EGFR), transforming growth factor-β (TGF-β), vascular endothelial growth factor (VEGF), platelet-derived growth factor (PDGF), IL-10, IL-6 and arginase-1, promoting tumor angiogenesis and tumor progression." (PMID 38792234, 2024). "However, there is also the potential to stimulate autocrine loops that promote tumor growth, as seen in increased expression of IL-6 and its receptor." (PMID 38397977, 2024). "We hypothesized that MCs traffic to high-grade tumors in an IL-6-dependent manner, and that perhaps newly recruited MCs serve as a local, replenishing source of IL-6 and eventual downstream immune cell activation and tumor site-specific fibrosis." (PMID 39195287, 2024). "Finally, analysis of common SASP markers in tumor tissues demonstrated that ADR markedly stimulated the expression of IL-6, IL-1β, and IL-1α, while TC significantly inhibited their expressions." (PMID 39364046, 2024). "IL-6 is a cancer-associated fibroblast (CAF)-specific secretory protein and a contributor to the dynamic crosstalk between tumour cells and the microenvironment, which is essential for tumour growth, invasion, and metastases." (PMID 38398148, 2024). "IL-6 expression in tumor cells is regulated by DNA methylation." (PMID 39199304, 2024). "Through our integrated clinical-biomarker–immunologic analyses derived from a diverse, pan-tumor cohort, we found that early increases in Th17 (IL-6, IL-17f), type 2 (IL-5, IL-13, IL-25), and type 1 (TNF-α) cytokines were associated with the development of grade ≥ 2 irAEs." (PMID 39403935, 2024). "IL-6 can be produced by multiple cell types including T cells, B cells, monocytes, fibroblasts, keratinocytes, endothelial cells, mesangial cells, adipocytes, and tumor cells." (PMID 38520006, 2024). "Activated CAFs can significantly promote tumor progression by secreting cytokines, such as IL-6." (PMID 39684264, 2024). "A previous study has shown that IL‐6 secreted by TAMs promotes tumour growth." (PMID 37974543, 2024). "Hopefully, these trials will soon provide insights into the efficacy and safety of IL-6/IL-6R neutralization as a therapeutic strategy for reactivating the T cell compartment and combating tumor development in patients refractory to first-line immune checkpoint inhibitor-based therapies." (PMID 39281678, 2024). "Thus, it is likely that serum IL-6 levels are not only derived from the tumor but are also produced to a considerable degree by PBMCs." (PMID 39518029, 2024). "This conclusion suggests that IL‐6 secretion may be spatially specific, even in the tumor microenvironment, cytokines in different regions have different expression levels." (PMID 39235042, 2024). "These microbiomes can induce macrophage migration into tumor tissues and activate the inhibited immune microenvironment through elevated IL-6, C-reactive protein (CRP), and vascular endothelial growth factor (VEGF) in systemic inflammation or elevated metabolites such as L-arginine in the TME." (PMID 39497925, 2024). "In addition, when tumor cells are suppressed through autophagy, they can also release IL-6, which further contributes to the pro-tumor effects of CAFs." (PMID 38649701, 2024).
tumor (continued). "In a lung cancer mouse model, tumor cells induce an inflammatory response in the kidneys by secreting nephrotoxic proteins, which increase the expression of IL-6 and monocyte chemoattractant protein-1 (MCP-1), resulting in glomerular capillary collapse and tumor antigen deposition." (PMID 39534084, 2024). "The adhesion of tumor spheroids to colon epithelium and myofibroblast monolayers modulated the proinflammatory cytokines IL‐1 beta, IL‐6, TNF‐alpha and radicals (ROS and NO) levels in a tumor grade‐dependent manner, with a significant increase of IL‐6 production in advanced CRC." (PMID 38962943, 2024). "IL-6 is highly expressed in GC and plays a significant role in promoting several tumour hallmarks." (PMID 39816318, 2024). "Additionally, IL-6 can influence the tumor microenvironment by promoting an immunosuppressive and pro-tumorigenic state." (PMID 38338683, 2024). "IL-6, IL-1β, and IL-8 all of which are known to be implicated in tumor progression were either downregulated or non-significantly upregulated." (PMID 39427065, 2024). "In this study, we found that HCC patients with a high pre-RT IL-6 concentration were prone to tumor progression, with a reduced OS time, which suggested that IL-6 may weaken the effects of RT." (PMID 39619013, 2024). "Also, the active derivatives caused cell cycle arrest at the S and G2/M phase with significant(p < 0.0001) increase in the expression levels of tumor suppressors miR-30C, and miR-107 and a tremendous decrease in oncogenic miR-25, IL-6 and C-Myc levels." (PMID 39209915, 2024). "The IL-1β/NFκB and IL-6/STAT3 signaling networks have well-established tumor-promoting functions." (PMID 39260693, 2024). "Indeed, specific interleukins (IL), such as IL-4, IL-6, and IL-13, induce collagen synthesis, contributing to tissue fibrosis and tumor progression." (PMID 39769286, 2024). "Basophils not only enhance humoral immune function but also liberate intracellular agents causing anti-tumor immunity, including the chemokines CCL3 and CCL4, which expedite CD8+ T-cell infiltration, and the chemokines TNF-α and IL-6, which enhance inflammatory anti-tumor responses." (PMID 39816393, 2024). "Conversely, Th2 secretes IL-6 and other factors that may negatively affect immunity by influencing the transcriptional activity of tumor cells through the AKT signaling pathway." (PMID 38623586, 2024). "Moreover, the activated phenotype of CAFs promotes tumor growth and metastasis by enhancing IL-6 secretion and establishing an inflammatory fibroblast niche." (PMID 38459511, 2024). "The mechanism for this phenomenon may be related to the fact that inflammatory factors, such as IL-6, promote the repair of DNA breaks after RT and reduce tumor cell apoptosis." (PMID 39619013, 2024). "In addition, cyclosporine, through the TGF-β and IL-6 overexpression pathways, directly contributes to tumor development and progression by affecting immune system downregulation." (PMID 38610636, 2024). "In addition, IL-6 and IL-8 produced by tumor cells have been shown to play immunosuppressive roles by impairing the activity and function of natural killer cells (NK cells)." (PMID 39206193, 2024). "Indeed, MAPK, JAK/STAT3, and PI3K are only a few of the signalling pathways that are activated by IL-6, and these pathways support the formation of tumours, have anti-apoptotic properties, and preserve phenotypic tumour progenitor cells." (PMID 39554609, 2024). "Pro-inflammatory cytokines like TNF-α and IL-6 play key roles in promoting tumor progression." (PMID 39493763, 2024). "Aberrant expression of IL-6 could promote tumor cell growth and metastasis by activating the IL-6/STAT3 signaling pathway." (PMID 38881895, 2024). "In addition, the tumor-driven cytokines IL-1, IL-6, and TNF-a suppress natural anticoagulants such as protein C and thrombomodulin, further exacerbating the coagulopathic state in brain cancer." (PMID 39766214, 2024).
tumor (continued). "V9 treatment also reduced the production of IL-6 but not TNFα in tumor-associated macrophages compared to PBS-treated mice." (PMID 39054536, 2024). "Measuring at least three cytokines, MCP-1, IFN-γ and IL-6 may be able to get very desirable information about principal responsiveness of the tumor to this treatment and, provided suppressed production of these cytokines, predict superior outcome." (PMID 39882242, 2024). "IL‐6 has been proposed as an important tumor‐promoting cytokine." (PMID 38217262, 2024). "IL-6 is a significant contributor to tumor growth and progression." (PMID 39872848, 2024). "In addition, TIM-3 participates in the M2 polarization of macrophages and promotes tumor growth via the NF-κB/IL-6 axis." (PMID 39085965, 2024). "It is thought that IL-6 is secreted locally from tumor cells and mainly by the immune system." (PMID 40777975, 2024). "Similarly, IL-6/JAK/STAT3 signaling pathway potently activates inflammatory response via tumor-infiltrating immune cells in the tumor immune microenvironment in CRC." (PMID 37507626, 2024). "In addition, IL-6 modifies the tumor microenvironment and facilitates epigenetic changes, further enhancing resistance mechanisms." (PMID 39336151, 2024). "In addition, senescent cells promote reprogramming of the embryonic state partially through IL-6, which can support tissue regeneration on the one hand and facilitate tumor development on the other 4, 13-15." (PMID 38323313, 2024). "Tumor expression of IL-6 was also found to be a marker of poor prognosis in cervical cancer." (PMID 39518029, 2024). "In addition to signal transduction in tumor cells, IL-6 trans-signaling in immune cells affects tumor progression." (PMID 38182653, 2024). "In addition, IL-6, recognised to be involved in tumour growth, metastasis and angiogenesis, has also been discovered to induce chemoresistance in BC cells." (PMID 39408212, 2024). "Overall, blockade of the IL‐6/IL‐6R pathway phenocopied O‐glycan truncation in tumor cells ex vivo." (PMID 37452653, 2024). "However, some studies also demonstrated that IL-6 can promote proliferation and invasion of tumor cells." (PMID 38360696, 2024). "In obesity, AT produces elevated levels of estrogen, pro-inflammatory cytokines (TNFα, IL-6, IL-1β), adipokines (leptin), and EVs, which may contribute to enhanced tumor invasiveness, proliferation, and metastasis." (PMID 39697630, 2024). "However, if we use TCR-T cells pre-treated with diABZI to be intravenous injected into the animal body, it greatly reduced the release of IL6 in the tumor microenvironment." (PMID 38615022, 2024). "Notably, we found that secreted OSM levels were higher than the secreted levels of IL-6 and IL-8, which are considered the most important proinflammatory interleukins produced by tumor cells." (PMID 38839865, 2024). "In the tumor microenvironment, TGF-β, IL-10, and IL-6 suppress NK cell activity and affect immunosuppressive cells and pro-inflammatory cytokines, decreasing the antitumor response of NK cells and promoting subsequent tumor evasion and progression." (PMID 39599846, 2024). "Furthermore, they showed that IL-6 promoted engraftment and dissemination of IL-6R expressing tumour cells in a mouse model, as well as promotion of MYC-driven lymphomagenesis." (PMID 38633747, 2024). "This implies that the ability of tumor development in the metastatic site by Jag2OE cells is exclusively dependent on the existence of mesothelial cells, which act as a reservoir for inflammatory stimuli such as IL-6." (PMID 38575576, 2024). "Blocking IL-6-stimulated STAT3 activation in these cells may lead to alterations in cytokines within the tumor microenvironment." (PMID 38426090, 2024). "However, more recently there has been emerging evidence that the presence of a high number of IL6+ immune cells at the invasive front of the tumour is predicative of better overall survival in CRC." (PMID 39766336, 2024).
tumor (continued). "Further gene-set enrichment analysis (GSEA) confirmed the upregulation in several cytokine-associated signalings including NF-κB, IL6-JAK-STAT3, IL2-STAT5, and IFN-α pathways, as well as epithelial mesenchymal transition (EMT), which is a crucial machinery for tumor-cell dissemination." (PMID 38926796, 2024). "IL-6 may also contribute to cell proliferation, survival, and chemoresistance of tumor cells by activating the Ras-ERK and PI3K-Akt pathways." (PMID 38520006, 2024). "There was also a trend for IL-6 and nodal positive primary tumor." (PMID 38233759, 2024). "The present data support the contention IL-6 signaling is upstream of a maladaptive cytokine and chemokine cascade capable of suppressing anti-tumor effector responses at the level of effector T cells and macrophages and promoting EMT and aggressive tumor behavior." (PMID 39114667, 2024). "Positive copies of IL6 mRNA were detected in both tumour epithelium and the surrounding stroma." (PMID 39766336, 2024). "This suggests that IL-6 may have a more direct impact on tumour behaviour or interact with other factors relevant to BC progression, which are not solely influenced by BMI." (PMID 39342063, 2024). "The tumor microenvironment (TME) is a critical source for factors like hypoxia (HIF-1α, NO), and signaling proteins derived from cells such as cancer-associated fibroblasts and macrophages (TGFβ, LCN2, IL-6, IL-1β, etc.)that influence EMT50." (PMID 39737957, 2024). "The hypothesis that albumin neo-structures generated in cancer might have an IL-6-inducing activity was analyzed by incubating tumor homogenates with albumin." (PMID 39518029, 2024). "The irradiation-induced increase in IL-6 and IL-8 secretion of the triple-negative cells in the present study might therefore have both a direct effect on the tumor cells and on the surrounding fat tissue." (PMID 39338222, 2024). "Moreover, Tf-CT-MEs also reduced the serum concentrations of inflammatory factors (TGF-β1, CCL2, TNF-α, and IL-6), and Tf-CT-MEs enhanced tumor targeting, promoted the deep penetration of drug components, and improved the treatment of cervical cancer." (PMID 38957318, 2024). "The HT1080 human fibrosarcoma cell line secretes several cachexia-related factors, such as growth differentiation factor 15 (GDF 15), interleukin 6 (IL-6), and activin A, and it has been reported that this tumor model has a similar phenotype to cancer cachexia." (PMID 39220755, 2024). "Moreover, fatty acid binding protein 4 (FABP4) secreted by adipose tissue enhances tumor stemness and aggressiveness by activating the IL-6/STAT3/ALDH1 axis in breast cancer, suggesting that plasma FABP4 is a new link between obesity and cancer risk." (PMID 39125923, 2024). "Notably, stromal senescence induced by p27 expression in fibroblasts can drive tumour progression through the IL‐6‐mediated recruitment of MDSCs, which subsequently impede anti‐tumour cytotoxic T cell responses." (PMID 39270064, 2024). "The Polycladia crinita extract mediated its promising anticancerous action by enhancing apoptosis and mitigating inflammation via VEGF, Notch 1, NF-кB, IL-6, Cyclin D1, Caspase 9 and Caspase 3 expression/level, which manifested in promoting the total survival rate and the tumor volume decrease." (PMID 38469406, 2024). "Furthermore, IL-6, CXCR4, CXCL8, and MMP-9 indicate higher diagnostic utility based on the area under the ROC curve (AUC) than well-established OC tumor markers, whereas CLDN18.2 can be used in novel targeted therapies for OC patients." (PMID 38673838, 2024).
tumor (continued). "This may suggest that, in the group with high serum IL-6 levels, there was an increase in local metabolic activity within the tumor tissue, and the molecules involved in tumor immunity were suppressed." (PMID 38510850, 2024). "Interestingly, a recent study unveiled a significant finding that interleukin-6 (IL-6) has the potential to inhibit HNSCC ferroptosis while simultaneously promoting tumor progression." (PMID 38429254, 2024). "Additionally, OASL regulates immune checkpoint ligand such as programmed death ligand 1 (PD-L1), through IFN-γ/STAT1 and IL-6/JAK/STAT3 pathways in tumor cells." (PMID 39286258, 2024). "Taken together, these findings demonstrated that TAMs promote tumor progression may by enhancing IL-6 secretion through IL-6." (PMID 38424624, 2024). "Analyses of NSCLC expression of hsa_circ_0000190, miR-1253, and interleukin 6 (IL-6) were conducted via a quantitative real-time polymerase chain reaction (qPCR) approach, while the ability of these tumor cells to resist DDP treatment was evaluated with a CCK-8 assay." (PMID 38440120, 2024). "The IL-6 concentration was contingent on distant metastases and the survival of patients with OC, with elevated levels observed in individuals with more advanced tumor stages and nodal metastases, particularly in those diagnosed with OSCC." (PMID 38673838, 2024). "Furthermore, apart from this physical impact, an increased body temperature alters the structure of tumor blood vessels by triggering IL-6 trans-signaling, leading to a more conducive environment for cytotoxic T cell movement into tumors." (PMID 39595094, 2024). "Moreover, blockade of EGFR/ERK/NFκB and EGFR/PI3K/NFκB signaling not only decreases IL6 and IL6R-associated chemoresistance in OC but also, when combined with an anti-IL6 antibody (Tocilizumab), potentiates the anti-tumor effect." (PMID 39766086, 2024). "IL-6 is produced by tumor cells, stromal cells and immune cells infiltrated in the TME." (PMID 38323313, 2024). "Moreover, the latest research shows that blocking the IL-6 factor produced by CAFs through autophagy favors anti-tumor immunity over immunotherapy." (PMID 39680287, 2024). "Furthermore, C-reactive protein is produced by hepatocytes in response to cytokines, especially IL-6, released by leukocytes within the tumor microenvironment." (PMID 38673838, 2024). "Furthermore, IL‐6 has been observed to induce tumor cells to produce Vascular Endothelial Growth Factor (VEGF), thereby facilitating the formation of blood vessels." (PMID 39223795, 2024). "The activation of the NF-κB signaling pathway in TAM and MDSCs induces the expression of pro-inflammatory factors (IL-10) and chemokines (CCL17, CCL2), while inhibiting the expression of inflammatory cytokines (TNF α, IL-1, IL-6, etc.), leading to M2 macrophage activation and tumor evasion." (PMID 38426090, 2024). "Additionally, CM treatment boosted moMDSCs production of IL-6, IL-10, and PGE2, soluble mediators associated with tumor-promoting inflammation." (PMID 38343540, 2024). "Monoclonal antibodies targeting IL‐6 (Siltuximab) and the IL‐6 receptor (IL‐6R) (Tocilizumab) have emerged as promising immunotherapeutic agents, utilisable as standalone treatments or in conjunction with traditional chemotherapy, for tumour therapy." (PMID 39270064, 2024). "Importantly, mechanistic investigations indicated that AQP3 promoted M2 macrophage polarization by the PPAR-γ/NF-κB axis, which affected tumor growth and migration via modulating IL-6 production." (PMID 39060229, 2024). "IL-6 as well as IL-8 can enhance tumor metastasis by promoting neoangiogenesis." (PMID 39007138, 2024).